IL33 (interleukin 33)
Diseases named in the same sentence as IL33 in open-access papers (continued):
Sharing a sentence is not in itself a finding about the gene and the disease.
brain injury (8 papers, 2018 to 2026). Acute and chronic (see also brain INJURIES, CHRONIC) injuries to the brain, including the cerebral hemispheres, CEREBELLUM, and brain STEM. "In this narrative review, we aimed to underline the diagnostic and prognostic importance of IL-33 in trauma, particularly in brain trauma." (PMID 32399302, 2020). "The therapeutic role of IL-33 from day 5 after traumatic brain injury was also confirmed by others with intranasal administration." (PMID 37968698, 2023). "Previous studies about the IL-33/ST2 signaling in brain injuries mainly focus on its effects within the CNS." (PMID 35432343, 2022). "The activation of IL-33/ST2 signaling also adjusts the adaptive immune responses after brain injuries." (PMID 35432343, 2022). "The use of pharmacological agents such as exogenous interleukin-33 (IL-33) has also been documented, showing improvements in cerebral lymphatic drainage and in the clearance of toxic proteins in mouse models with traumatic brain injuries." (PMID 41596575, 2026). "The current study reveals a previously unknown function of IL-33/ST2 signaling in neuroprotective effect during neonatal HI brain injury." (PMID 32859229, 2020). "Therefore, we speculate that the protective effects of celastrol in AIS-induced brain injury are related to an IL-33/ST2 axis-mediated microglia/macrophage M2 polarization." (PMID 29540209, 2018).
chronic asthma (8 papers, 2013 to 2024). An asthma that is characterized by the development of persistent airway inflammation and recurrent attacks of breathlessness and wheezing, which vary in severity and frequency. "These cells are key players in the inflammatory response in lung tissue, and our data provide novel evidence that IL-33 drives the distal airway inflammation associated with an acute exacerbation of chronic asthma." (PMID 23936781, 2013). "The crucial network of this interaction between epithelial cells and ILC2s generates sustained IL-33 production, which is key in the development of persistent/chronic asthma." (PMID 32931477, 2020). "Collectively, these data indicate that in this model of an acute exacerbation of chronic asthma, IL-33 drives activation of AM and has an important role in the pathogenesis of airway inflammation." (PMID 23936781, 2013). "We investigated the role of interleukin-33 (IL-33) in airway inflammation in an experimental model of an acute exacerbation of chronic asthma, which reproduces many of the features of the human disease." (PMID 23936781, 2013). "Interestingly, CycloZ significantly reduced the expression of IL-33, a cytokine that promotes Th2 cytokine production and is critical in chronic asthma pathogenesis." (PMID 39682780, 2024). "In addition, blockade of IL-33 signaling has been shown to limit the development of ILC2-mediated chronic asthma, with the administration of IL-33 activating ILC2-dependent lung inflammatory responses and goblet cell hyperplasia." (PMID 34194431, 2021). "In the second part of this work, we investigated whether activation of AM in an experimental acute exacerbation of murine chronic asthma might be related to increased expression of IL-33." (PMID 23936781, 2013). "Therefore, we hypothesized that CD146 may mediate airway remodeling in chronic asthma in a manner that was dependent on the IL-33 signaling pathway." (PMID 32793232, 2020). "However, the role of IL-33 in airway inflammation in a model that simulates a clinical acute exacerbation of chronic asthma has not previously been studied." (PMID 23936781, 2013).
dengue (8 papers, 2019 to 2023). "PGD2 significantly increased infectivity of ILC2 and acted with IL-33 to increase infectivity of ILC2 compared to dengue virus infection in unstimulated ILC2." (PMID 35869167, 2022). "For instance, at higher viral loads in HCV and Dengue fever, elevated levels of IL-33 were clearly detected." (PMID 35056005, 2022). "Furthermore, in ST2 knocked out mice, dengue pathologies were less severe compared to wild-type mice, and IL33 was proposed to mediate dengue severity." (PMID 36228040, 2022). "TM30089 significantly reduced dengue virus infection of exogenous PGD2 and IL-33 treated ILC2." (PMID 35869167, 2022). "Our first priority was to compare the levels of IL-1b, IL-2, IL-4, IL-6, IL-8, IL-10, IL-12p70, IL-17A, IL-33, CD14, CD54, CD62E, CD62L, CD62p, CD106, CD121b, CD154, CD178, GM-CSF, IFN-g, MIF, ST2 and TNF in plasma samples of dengue group, OF group and Healthy group." (PMID 33809042, 2021).
heartburn (8 papers, 2016 to 2025). "Our previous studies showed that IL-33 mRNA and protein levels were increased in reflux esophagitis patients and participated in the exaggeration of inflammation." (PMID 36110250, 2022). "We have recently reported that the expression of IL-33 was upregulated in esophageal epithelial cells in reflux esophagitis." (PMID 26986625, 2016). "Further studies are needed to explore the mechanisms by which IL-33 is regulated in patients with heartburn and how IL-33 levels are related to the generation of heartburn symptoms." (PMID 27111066, 2016). "In summary, we showed that IL-33 levels were upregulated in patients with heartburn." (PMID 27111066, 2016). "Upregulated IL-33 in heartburn patients is related to the symptoms." (PMID 27111066, 2016). "However, further examinations are needed to clarify the function of IL-33 and to elucidate how IL-33 is involved in the development of heartburn symptom." (PMID 27111066, 2016). "We recently showed that IL-33 in esophageal mucosa is upregulated in reflux esophagitis." (PMID 27111066, 2016). "IL-33 expression and the mean ICS were significantly increased in the mucosa of patients with heartburn compared to that of the control." (PMID 27111066, 2016). "In a rat model of gastroesophageal reflux, which simulates the progression from normal to low-grade dysplasia, high-grade dysplasia, and EAC, IL-33 increased gradually, suggesting its involvement in the entire process from esophageal inflammation to tumorigenesis of EAC." (PMID 37296602, 2023). "The expression of IL-33 in the middle and distal esophageal mucosa of patients with heartburn without mucosal break and control samples was examined using real-time RT-PCR and immunofluorescence." (PMID 27111066, 2016). "Two thirds of the heartburn patients were PPI refractory in this study and thus the use of PPI might modulate the level of IL-8 or other cytokines except for IL-33." (PMID 27111066, 2016). "The IL-33 mRNA levels were not different between the heartburn patients who were taking a PPI and those who were not." (PMID 27111066, 2016). "However, IL-33 expression in patients with heartburn without mucosal injury and its relationship with intercellular space (ICS) have never been examined." (PMID 27111066, 2016). "However, we did evaluate ICS as a marker of GER and the IL-33 level was correlated with ICS, indicating that GER was related to the upregulation of IL-33 and heartburn in this study." (PMID 27111066, 2016). "However, we focused on heartburn in this study, and based on the data of DIS and IL-33 in heartburn patients, even in those patients with PPI treatment, it is possible that IL-33 levels might be related to the development and persistence of GERD symptoms regardless of the use of PPI." (PMID 27111066, 2016). "However, the mRNA levels of IL-8, IL-6, MCP-1 and RANTES were not upregulated in heartburn patients regardless the use of PPI versus controls in this study, even though the IL-33 mRNA level in heartburn patients still correlated with IL-8 and IL-6 levels." (PMID 27111066, 2016).
infarction (8 papers, 2013 to 2024). A localised pathological necrosis of tissue resulting from obstruction of the blood supply usually by a thrombus, an embolus, or vascular torsion. "Subcutaneous injection of IL-33 reduced infarct volume, fibrosis, and apoptosis of myocardium after infarction due to coronary ligation, while the presence of sST2 was able to counteract the positive effects of IL-33 in a dose-dependent manner." (PMID 24335613, 2013). "The IL-33/ST2 signaling pathway is involved in various adverse pathophysiological processes after infarction, such as fibrosis, inflammation, and hypertrophy, which are important targets for a variety of neuroendocrine antagonists currently available to improve the prognosis of MI patients." (PMID 36225958, 2022). "It has also been implicated in the expression of the myofibroblast-activating interleukin IL-33, with Cre/Lox-mediated YAP knockout significantly attenuating IL-33 expression and scarring in a murine model of post-infarction cardiac fibrosis." (PMID 37874141, 2023). "Similarly, no NG2+/IL33+/Ki67+ triple positive OPCs were identified in the WM of Sham-operated rats, or the WM contralateral to infarction, while they were abundant in affected WM (17.00 ± 5.5/mm2)." (PMID 39043661, 2024).
lupus nephritis (8 papers, 2017 to 2024). Glomerulonephritis in the context of systemic lupus erythematosus. "In the current study, MRL/lpr mice as animal models, and HK-2 human renal tubular epithelial cells were stimulated by interleukin-33 (IL-33) to mimic the cellular model of lupus nephritis." (PMID 36421424, 2022). "sST2 levels rise in an attempt to counteract the sudden increase in extracellular IL-33, as suggested by immunostaining from patients with lupus nephritis, where an increase in both IL-33 and sST2 was observed." (PMID 35328556, 2022). "To verify the ameliorating effect of quercetin on lupus nephritis phenotype, we first used recombinant human IL-33 to induce fibrosis and inflammation in HK-2 renal tubular epithelial cells." (PMID 36421424, 2022). "In comparison to the control group, young NZB/W F1 mice administered with IL-33 had a better survival rate as well as reduced proteinuria level and lupus nephritis." (PMID 33182616, 2020). "Increased serum IL-33 has been reported only in Chinese patients with SLE, and a role of IL-33 has been suggested in the interstitial renal fibrosis that characterises later stages of lupus nephritis." (PMID 29422069, 2018). "Further investigations on the direct impact of the IL-33/ST2 pathway in lupus nephritis are required." (PMID 28387719, 2017). "Notably, IL-33 treatment upregulated integrin α4β7 and Areg expression in ILC2s, thereby enhancing survival and reducing inflammation in lupus nephritis." (PMID 38806623, 2024). "Our ex vivo functional assays, coupled with evidence that pDCs infiltrate the inflamed kidneys in SLE, raise the possibility that IL-33–decorated NETs trigger intrarenal type I IFN production in lupus nephritis, as recently suggested by single-cell transcriptomic studies." (PMID 34554930, 2021). "Interestingly, we found that IL-33 NETs were predominantly localized within the tubulointerstitium, and tubulointerstitial inflammation has been correlated with pDC infiltrates and poor prognosis in lupus nephritis." (PMID 34554930, 2021). "The expressions of IL-33 as well as its receptor, ST2, are significantly upregulated in SLE patients and in patients with lupus nephritis." (PMID 35328556, 2022). "After a regiment of two IL-33 injections at 14 and 17 weeks, a significant increase in ILC2 was observed, together with lower scores of lupus nephritis and a decrease in mortality." (PMID 35328556, 2022). "However, quercetin reversed the expression of IL-6, IL-8, IL-33, and HMGB1 induced by IL-33, indicating that quercetin exerts anti-fibrotic and anti-inflammatory effects in the cellular model of lupus nephritis, as opposed by IL-33." (PMID 36421424, 2022). "However, quercetin reversed the expression of NLRP3, ASC, caspase-1, N-GSDMD, and IL-1β induced by IL-33, indicating that quercetin can relieve inflammasome- and GSDMD-mediated pyroptosis in the cellular model of lupus nephritis." (PMID 36421424, 2022).
metabolic syndrome (8 papers, 2019 to 2024). A cluster of metabolic risk factors for CARDIOVASCULAR DISEASES and TYPE 2 DIABETES MELLITUS. "The aim of our study was to investigate the association between adiponectin and interleukin-33 in patients with metabolic syndrome." (PMID 36614933, 2022). "Increased levels of IL-33 were positively associated with metabolically unhealthy overweight/obese phenotype and several metabolic syndrome risk factors." (PMID 33541367, 2021). "As adiponectin has previously been shown to exert an anti-inflammatory and insulin-sensitizing effect, a possible relationship between interleukin-33 and adiponectin in metabolic syndrome patients was assessed." (PMID 39171751, 2024). "In the subgroup of patients with low adiponectin, we observed less pronounced characteristics of metabolic syndrome simultaneously with significantly higher values of interleukin-33 compared to the subgroup of patients with high adiponectin." (PMID 36614933, 2022). "IL-33 was also demonstrated in the B6.Lepob/ob mouse model to protect from metabolic syndrome, induce Th2 response and polarize macrophages to an M2 phenotype, but no data on Tregs was reported." (PMID 31191312, 2019). "The increased concentration of IL-33 and IL-25 in the VAT observed in our study in association with the low-grade inflammation linked to metabolic syndrome constitute a primary signal vital for ILC2 activation." (PMID 30755607, 2019). "Here, the levels of IL-33 in patients with T2D with either controlled or uncontrolled metabolic syndrome were compared with normoglycemic controls, and it was observed that IL-33 was significantly decreased in both T2D groups, whereas ST2 was significantly increased." (PMID 39171751, 2024). "We also suggest that both interleukin-33 and adiponectin may be used to predict the inflammatory status in the early stage of metabolic syndrome." (PMID 36614933, 2022). "Circulating levels of IL-33 in overweight/obese people with various metabolic phenotypes were different and was significantly elevated only in MUOO population; IL-33 levels were positively correlated with MUOO phenotype and metabolic syndrome risk factors in overweight/obese Chinese adults." (PMID 33541367, 2021). "In addition to the analysis of IL-33 expression in adipose tissue, serum IL-33 levels have been reported to be significantly reduced in patients with T2D, irrespective of the presence of symptomatic metabolic syndrome." (PMID 39171751, 2024).
Nephropathy (8 papers, 2016 to 2024). A nonspecific term referring to disease or damage of the kidneys. "Two animal studies revealed that both serum and renal tissue IL-33 levels are elevated in DM rats with contrast-induced nephropathy." (PMID 28387719, 2017). "Recently, a new member of the IL-1 family, IL-33, is presented as an alarmin molecule that invites inflammatory cells to the kidney in cisplatin-induced nephropathy." (PMID 26989334, 2016). "Later on, Shruthi and colleagues investigated the serum levels of several cytokines, including IL-33 in 125 T1DM subjects, 96 of which featured microvascular complications (retinopathy and nephropathy in particular) and 29 without such concurrent problems, as well as in 76 controls." (PMID 30769901, 2019).
pancreatic ductal adenocarcinoma (8 papers, 2017 to 2025). An infiltrating adenocarcinoma that arises from the epithelial cells of the pancreas. "For example, in an orthotopic model of pancreatic ductal adenocarcinoma, deleting IL-33 led to increased tumor burden due to reduced recruitment of ILC2s." (PMID 39574565, 2024). "IL-33 levels, specifically elevated in human pancreatic ductal adenocarcinoma, correlate positively with tumor inflammation." (PMID 39068459, 2024). "We explored IL-33 and sST2 as a potential prognostic marker in patients with metastatic and locally advanced pancreatic ductal adenocarcinoma (PDAC)." (PMID 30426271, 2018). "For instance, while recombinant IL-33 treatment reduces tumor burden in pancreatic ductal adenocarcinoma, in BCa, IL-33 may exacerbate the ILC2-mediated recruitment and polarization of MDSCs." (PMID 39574565, 2024). "Besides, miR-940 can inhibit the growth of pancreatic ductal adenocarcinoma via targeting MyD88 that involved in IL-33 mediated type 1 helper T cells (Th1) differentiation (Th1 is pivotal in cellular immunity)." (PMID 28222782, 2017). "In pancreatic ductal adenocarcinoma (PDAC), the intratumoral fungal microbiome, such as Malassezia and Alternaria, has been shown to increase the level of interleukin-33 (IL-33)." (PMID 39995663, 2025). "IL-33-stimulated macrophages are the primary source of CXCL3, which is highly upregulated in pancreatic ductal adenocarcinoma compared to other cancer types." (PMID 39068459, 2024).
peritonitis (8 papers, 2018 to 2025). Inflammation of the peritoneum (tissue that lines the abdominal wall and covers most of the organs in the abdomen). "Lastly, a murine model of IL-33 induced peritonitis was used to assess the effects of isoprenylation inhibition on eosinophil and neutrophil influx." (PMID 41459508, 2025). "To investigate the possible role isoprenylation plays in IL-33-mediated inflammation in vivo, we conducted a model of IL-33-induced peritonitis." (PMID 41459508, 2025). "They observed IL-33 treatment significantly reduced neutrophil influx in MSU-induced mouse peritonitis model." (PMID 33204337, 2020). "To test the importance of IL-33-induced glycolysis in vivo, we used a model of IL-33-induced peritonitis in which neutrophil recruitment is mast cell-dependent." (PMID 30619366, 2018). "Interestingly, a large number of CD11b+Gr1intF4/80+ MDSCs was detected in the IL-33-treated mice, and adoptive transfer of IL-33-induced MDSCs markedly inhibited the IL-1β production in MSU-induced peritonitis." (PMID 30863362, 2019). "Furthermore, adoptive transfer of IL-33-induced MDSCs (CD11b+Gr1intF4/80+) markedly inhibited IL-1β production in MSU-induced peritonitis." (PMID 30863362, 2019). "Interestingly, an IL-33-induced peritonitis model that elicits eosinophil and neutrophil influx showed that FGTI-2734, but not simvastatin, could greatly reduce inflammation." (PMID 41459508, 2025). "Moreover, consistent with the promotion of EMT by CAFs-derived IL-33 in vitro, there were also decreased expression of ZEB2 in peritoneal tumors derived from GC cells mixed with CAFs-siRNA/IL-33 than in tumors derived from GC cells mixed with CAFs-siRNA/NC." (PMID 31659258, 2020). "Besides that, a large number of anti-inflammatory MDSCs with CD11b+Gr1intF4/80+ phenotype was observed in the IL-33-treated mice, and adoptive transfer of IL-33-induced MDSCs (CD11b+Gr1intF4/80+) markedly inhibited the IL-1β production in MSU-induced peritonitis." (PMID 30863362, 2019).
respiratory failure (8 papers, 2013 to 2026). The significant impairment of gas exchange within the lungs resulting in hypoxia, hypercarbia, or both, to the extent that organ tissue perfusion is severely compromised. "Tozorakimab was well tolerated and the OR for risk of death or respiratory failure with treatment versus SoC was 0.55 (80% CI 0.27–1.12; p=0.26), while the OR was 0.31 (80% CI 0.09–1.06) in patents with high baseline serum IL-33/sST2 complex levels." (PMID 37868151, 2023). "The secondary outcome of risk of death or respiratory failure at day 29 was assessed by baseline levels of the serum biomarker IL-33/sST2 complex." (PMID 37868151, 2023). "Such IL-1β, IL-18, and IL-33 were common inflammatory factors, our study showed that all of these could be increased during P-ALI, and even leading to respiratory failure." (PMID 38826806, 2024).